HIF1A (hypoxia inducible factor 1 subunit alpha)
Diseases named in the same sentence as HIF1A in open-access papers (continued):
Sharing a sentence is not in itself a finding about the gene and the disease.
Arrhythmia (6 papers, 2016 to 2025). Any cardiac rhythm other than the normal sinus rhythm. "Interventional strategies focused ontargeting HIF-1α hold promise as a means of managing patients sufferingfrom this form of arrhythmia." (PMID 40026494, 2025). "This review provides a detailed overview of the functional roleof HIF-1α in AF and discusses its potential therapeutic implications,thereby laying a foundational knowledge base to support future therapeuticstrategies against this disruptive form of arrhythmia." (PMID 40026494, 2025).
atopic dermatitis (6 papers, 2018 to 2025). "To investigate how HIF‐1α is up‐regulated in allergic dermatitis, we first examined the effects of FITC exposure on the expression of HIF‐1α in HaCaT cells." (PMID 29993193, 2018). "HIF-1α deficiency attenuated epidermal hyperplasia and type 3 inflammation in the imiquimod (IMQ)-induced psoriasiform model but had little effect in DNFB-induce contact hypersensitivity and MC903-induced atopic dermatitis model." (PMID 41595601, 2025). "On the basis of these results, the authors suggest the promising possibility of HIF-1α/STAT5 as therapeutic targets and their decoy ODN as a potential therapeutic tool for atopic dermatitis." (PMID 37799329, 2023). "To conclude, calycosin may be a potential drug for the treatment of allergic dermatitis by regulating tight junctions via inhibiting the expression of HIF‐1α, and as a consequence, HIF‐1α and TJs might be possible therapy targets for allergic dermatitis." (PMID 29993193, 2018).
benign prostatic hyperplasia (6 papers, 2010 to 2025). A non-cancerous nodular enlargement of the prostate gland. "Thus, the pathogenic role of HIF-1α in prostatic hyperplasia gains extra support by the observed elevation of TNF-α and IL-1β by testosterone." (PMID 30154949, 2018). "IH can also promote the accumulation of the transcriptional activator hypoxia-inducible factor 1α (HIF-1α), which is a key factor in the progression of prostate hyperplasia and a potential therapeutic target in BPH." (PMID 24667846, 2014). "In the present study, QC treatment was shown to inhibit the activation of the HIF-1α pathway in prostatic hyperplasia tissues, with QC significantly suppressing the mRNA and protein expression of HIF-1α." (PMID 24944609, 2014). "In order to investigate whether the immunoreactive HIF1β co-localizes with HIF1α in benign prostate tissue, we selected two cases of benign prostate hyperplasia for double immunostaining." (PMID 20663134, 2010). "Although no HIF1α expression was seen in normal prostatic tissue, the HIF1α protein expression seen in benign prostatic hyperplasia (BPH) and prostatic intra-epithelial neoplasia (PIN) results in poor specificity." (PMID 23342109, 2013).
choroidal neovascularization (6 papers, 2014 to 2024). An eye disorder described by the growth of new blood vessels that originate from the choroid through a break in the Bruch membrane into the sub–retinal pigment epithelium (sub-RPE) or subretinal space. "Studies in animal models have further supported these findings, showing that resveratrol alleviates choroidal neovascularization (CNV) by modulating the hypoxia-inducible factor 1-alpha (HIF-1α)/VEGF/VEGFR2 pathway." (PMID 39765886, 2024). "A recent study reported that HIF-1α knockout mice showed a decreased VEGF production compared to wild type animals in a model of laser choroidal neovascularization (CNV)." (PMID 29332242, 2018). "Recently, chrysin was also found to inhibit laser-induced choroidal neovascularization (CNV) and down-regulate HIF-1α and VEGF expression." (PMID 32748894, 2020). "By downregulating the hypoxia-inducible factor 1-alpha/vascular endothelial growth factor/vascular endothelial growth factor receptor 2 (HIF-1α/VEGF/VEGFR2) signaling pathway, flavonoids effectively reduce the expression of critical mediators of choroidal neovascularization (CNV)." (PMID 39765886, 2024). "Isolectin-B4, Ki67, HIF-1α, VEGF, NMDAR1, and albumin were assessed by immunofluorescence (IF), Western blot (WB), Optical coherence tomography (OCT), and fluorescein angiography (FA) to evaluate retinal structure, fluorescein leakage, and choroidal neovascularization (CNV)." (PMID 34502266, 2021).
chronic rhinosinusitis (6 papers, 2014 to 2024). Chronic form of sinusitis. "Goblet cell or mucous metaplasia is one of major histopathologic changes in chronic rhinosinusitis, and activation of HIF-1α mediates the associated changes via the extracellular signal-regulated kinase 1/2 signaling pathway." (PMID 24840724, 2014). "In addition, the role of HIF-1α in AR and chronic sinusitis will be crucial, making it a pivotal target for therapeutic interventions in these conditions." (PMID 38469312, 2024).
diabetic foot ulcers (6 papers, 2019 to 2025). "Overexpression of HIF-1α promotes invasion, migration, proliferation, and tubule formation ability of endothelial cells, and it has a role in promoting tissue angiogenesis and diabetic foot ulcer healing." (PMID 38107519, 2023).
follicular thyroid cancer (6 papers, 2013 to 2024). "It has also been shown in follicular thyroid cancer cell lines that epithelial–mesenchymal transition is induced by HIF-1α activation." (PMID 32847004, 2020). "To determine whether S1P-induced HIF-1α expression is a common feature in follicular thyroid cancer cells, we treated FTC-133 cells with S1P." (PMID 23824493, 2013). "This study investigated the significance of serum hypoxia-inducible factor (HIF)-1α/HIF-2 α and Chitinase 3-Like protein 1 (YKL-40) levels in the assessment of vascular invasion and prognostic outcomes in patients with Follicular Thyroid Cancer (FTC)." (PMID 39277981, 2024). "They demonstrated that HIF1-α expression was higher in ATC, which showed undifferentiated characteristics compared to other tumor types, such as PTC and follicular thyroid cancer (FTC)." (PMID 36428988, 2022). "In follicular thyroid cancer cell lines, GDC-0941, a PI3K inhibitor that sequentially inhibits HIF-1α pathways, has been found to attenuate metastatic behavior." (PMID 32847004, 2020). "Several studies reported that S1P–increased HIF1α expression was abolished by S1PR1/S1PR3 inactivation or S1PR3 silencing in liver hepatocellular carcinoma cells and thyroid follicular carcinoma cells, respectively." (PMID 31383843, 2019).
gestational diabetes (6 papers, 2013 to 2026). Carbohydrate intolerance first diagnosed during pregnancy. "The effect of HIF1α excessive activation is to increase the expression of genes encoding proteins directly involved in the glycolysis which may lead to pathological changes in glucose metabolism observed in gestational diabetes." (PMID 33520443, 2021). "Our previous study showed decreased WWOX expression and an increase of HIF1A and its targets glycolysis genes in gestational diabetes mellitus (GDM) patients in comparison to control." (PMID 35328751, 2022). "It is also worth mentioning that gestational diabetes patients were characterized by high HIF1A expression and its target genes." (PMID 36271927, 2022). "However, data on the effects of gestational diabetes on the WWOX/HIF1 α signaling pathway are limited, and the role of the HIF1α pathway in GDM remains unclear." (PMID 38234430, 2023). "Placental expression of MMP14 is greater in pregnancies complicated by gestational diabetes mellitus and, in vitro it is induced by insulin and IGF-II in vitro and HIF-1α." (PMID 24391823, 2013).
hemorrhage (6 papers, 2015 to 2024). Loss of blood from the vascular compartment to the exterior or into nonvascular body space as a result of rupture or severance of the blood vessels. "Finally, HIF-1α-mediated hypoxia-related signaling cascade was upregulated in the bladder after ifosfamide insult, consistent with the hemorrhage associated with hemorrhagic cystitis." (PMID 30733505, 2019). "Notably, the brain-specific knock-in of the R132H mutation was associated to hemorrhages in the presence of increased HIF-1α expression and deficient collagen maturation and basement membrane function." (PMID 25849072, 2015). "We investigated the association between digital H-score of HIF1α, VEGF, and bFGF with hemorrhage and TILs." (PMID 33552976, 2020). "Generally, they appear to lack the ability to instruct sufficient supportive stroma for their growth, resulting in large areas of necrosis and hemorrhagic cysts surrounded by hypoxic regions as evidenced by the presence of nuclear HIF1α." (PMID 31611367, 2019). "In this study, not surprisingly, HIF-1α gene expression was elevated alongside the downstream target genes in the lung after trauma and hemorrhage." (PMID 38365865, 2024).
Hyperinsulinemia (6 papers, 2015 to 2025). An increased concentration of insulin in the blood. "In addition to hypoxia, this could be due to the more severe hyperinsulinemia of obese mice, since it is known that insulin increases HIF-1α mRNA in adipocytes, or other different stimuli." (PMID 26619907, 2015). "Hyperinsulinemia alone did not affect HIF-1α activation or the metabolic response to hypoxia." (PMID 30175272, 2018).
hypertrophic cardiomyopathy (6 papers, 2015 to 2026). A condition in which the myocardium is hypertrophied without an obvious cause. "In stark contrast, deletion of Hif1a together with Vhl (fatVHL1Ako) significantly exacerbated hypertrophic cardiomyopathy and resulted in much earlier onset of death with a median survival time of only 4 weeks for fatVHL1Ako mice." (PMID 25852648, 2015). "In accordance with HIF-1α induction, elevated KHK-C and SF3B1 levels were also detected in biopsies from patients suffering from aortic stenosis or hypertrophic cardiomyopathy." (PMID 32733884, 2020).
intracerebral hemorrhage (6 papers, 2016 to 2024). A cerebrovascular disorder characterized by bleeding into one or both cerebral hemispheres including the basal ganglia and the cerebral cortex. "The PI3K/Akt and MAPK signaling pathways, and HIF-1α, also play critical roles in the prevention of BBB disruption, which is one of the main causes of intracerebral hemorrhage." (PMID 33123006, 2020). "Similarly, the HIF-1α protein was obviously expressed in perihematomal neurons of rats with intracerebral hemorrhage." (PMID 36570456, 2022). "Secondary outcomes include early neurologic improvement at 24 and 48 h, disability at 3 months, rate of symptomatic intracerebral hemorrhage, feasibility (proportion of patients completing RIC), tolerability after RIC and at 72 h, blood levels of HIF-1α, and HSP27 at 24 h and 72 h." (PMID 34803872, 2021). "Notch activation endangers neurons by modulating NF-κB and HIF-1α pathways, however, the role of Notch signaling in activating JNK/c-Jun following intracerebral hemorrhage (ICH) has not been investigated." (PMID 27655677, 2016).
invasive carcinoma (6 papers, 2004 to 2025). A carcinoma that is not confined to the epithelium, and has spread to the surrounding stroma. "Further analyses by the HIF1‐α IHC marker showed that the breast samples which have been positively scored by CDP (such as atypia or invasive carcinoma) expressed considerable levels of HIF1‐α." (PMID 35079624, 2022). "HIF-1α up-regulation in response to LPS-mediated stimulation and periinflammatory expression in invasive carcinomas suggest its involvement in inflammatory events." (PMID 18983642, 2008). "To validate the in vitro findings in a clinical setting, we analyzed the protein expression of ERRα, PGC-1α, HIF-1α, and P-gp in a TMA containing 144 invasive carcinoma cases and 24 invasive lobular carcinoma cases." (PMID 40723264, 2025). "There was a significant positive correlation in 253 invasive carcinomas from tissue microarrays between DEC1 and tumour grade (P=0.01), HIF-1α (P=0.04) and the hypoxically regulated gene angiogenin (P<0.0001)." (PMID 15328513, 2004). "We used immunohistochemistry to examine the expression of the hypoxia markers HIF-1α, CAIX and Glut-1 in DCIS and available invasive carcinoma lesions of 32 BRCA1, 16 BRCA2 and 77 non-BRCA mutation-related cases." (PMID 23409121, 2013).
ischemia reperfusion injury (6 papers, 2020 to 2026). Adverse functional, metabolic, or structural changes in ischemic tissues resulting from the restoration of blood flow to the tissue (reperfusion), including swelling; hemorrhage; necrosis; and damage from free radicals. "The HIF-1α/BNIP3 axis protects the kidney from ischemia-reperfusion injury (IRI) by promoting ER autophagy (reticulophagy)." (PMID 41602837, 2026). "In this study, we observed elevated expression of Hypoxia-inducible Factor 1-alpha (HIF-1α) in the kidneys of mice subjected to ischemia-reperfusion injury (IRI)." (PMID 38710691, 2024). "Experimental evidence indicates that HSP90AA1 (Heat Shock Protein 90α subtype), an ATP-dependent molecular chaperone, participates in the cascade reactions of ischemia-reperfusion injury by modulating conformational changes of transcription factors such as NF-κB and HIF-1α." (PMID 40808948, 2025). "During hypoxic conditions, such as ischemia-reperfusion injury that often occurs in AKI, HIF-1α is stabilized and activates a wide range of genes involved in adaptive responses." (PMID 38710691, 2024). "In this study, the significant changes in the expression of HIF-1α, p-AkT and p-GSK-3β/GSK-3β ratio in the heart homogenates of ischemia-reperfusion injury subjected rats were also observed." (PMID 36542041, 2022).
lactic acidosis (6 papers, 2020 to 2025). Metabolic acidosis characterized by the accumulation of lactate in the body. "Although lactic acidosis causes stronger HIF1α protein expression compared to hydrochloric acidosis, it does not lead to increased glucose uptake due to the strong upregulation of TXNIP, a very potent suppressor of GLUT1 and a HIF1α destabilizing protein." (PMID 38195466, 2024). "Hypoxic HIF-1α-reprogrammed metabolism causes outcomes such as lactic acidosis, specific ROS productions, increased lipid peroxidation, energy shortage, changing redox state, etc., and may lead to apoptotic death of the cell." (PMID 34822413, 2021). "The stronger upregulation of HIF-1α, an indicator of energy shortage, during lactic acidosis compared to hydrochloric acidosis supports this conclusion." (PMID 38195466, 2024). "A-427 cells cultured under lactic acidosis or hypoxia increased total and pAMPK levels, as well as HIF-1α protein levels in comparison with neutral lactosis and normoxia." (PMID 32596143, 2020). "The diminished mRNA levels of HIF-1α correlated with an increased expression of citrate synthase, alongside with the increase of mitochondrial respiration rate in A-427 cells cultured under lactic acidosis and normoxia; nonetheless, HIF-1α protein levels presented a slight increase." (PMID 32596143, 2020). "Hypoxia, a chemoresistance factor, involves mechanisms such as HIF-1α, microRNA suppression, MDR-1 overexpression, lactic acidosis, NF-κB overexpression, changes in mitochondrial dynamics, and dysregulated glycolysis." (PMID 40507826, 2025). "Under lactic acidosis and normoxic conditions the reduced expression of GLUT1 and monocarboxylate transporters was possibly promoted by the reduction of both HIF-1α and AMPK protein levels." (PMID 32596143, 2020). "To figure out how the metabolism of tumor and fibroblast cells was regulated under lactic acidosis, we evaluated AMPK, HIF-1α, and CS transcript levels on these cells after 48 h of incubation under the four culture conditions." (PMID 32596143, 2020). "A-549 cells cultured under lactic acidosis or hypoxia increased HIF-1α protein levels, but pAMPK levels did not change in comparison with neutral lactosis and normoxia." (PMID 32596143, 2020). "We also found that under lactic acidosis, MRC-5 cells diminished total AMPK and HIF-1α levels independent of oxygen tension." (PMID 32596143, 2020). "MCF-7 cells cultured under lactic acidosis or hypoxia did not change total and phosphorylated AMPK, nor HIF-1α protein levels in comparison with neutral lactosis and normoxia." (PMID 32596143, 2020).
laryngeal squamous cell carcinoma (6 papers, 2012 to 2023). A squamous cell carcinoma that arises from the larynx. "Similar findings have been reported in laryngeal squamous cell carcinomas for other binomial LncRNA/mRNA transcripts, such as: NR_003919/PIK3R1, NR_027340/ITGB1, MIR31HG/HIF1A, and SOX2‐OT/DDIT4." (PMID 33433063, 2021). "The present study explored the expression and correlation of HIF-1α and MDR1/P-gp in human laryngeal squamous cell carcinoma (LSCC) tissues." (PMID 23946810, 2013). "The present study aimed to evaluate the expression of hypoxia-inducible factor-1α (HIF-1α) and MDR1/P-glycoprotein (P-gp) in human laryngeal squamous cell carcinoma (LSCC) tissues, and also to investigate the regulation of MDR1 gene expression by HIF-1α in Hep-2 cells under hypoxic conditions." (PMID 23946810, 2013).
metastasis (6 papers, 2014 to 2023). The spread or migration of cancer cells from one part of the body (where they first appeared) to another. "Research reported that HIF-1α (hypoxia inducible factor-1α) expression in liver metastasis determines poor prognosis of CRC liver metastasis patients." (PMID 36798788, 2023). "The aim of this study was to elucidate a possible mechanism of activated HSCs on augmenting tumor malignancy and to investigate the association of HIF-1α expression between primary CRC and liver metastasis on CRLM patient prognosis." (PMID 32895059, 2020).
oligodendroglioma (6 papers, 2008 to 2022). A well-differentiated (WHO grade II), diffusely infiltrating neuroglial tumor, typically located in the cerebral hemispheres. "Furthermore, HIF-1α overexpression is significantly correlated with highly aggressive disease and poor prognosis in some cancer types, including breast, ovarian, oligodendroglioma, and oropharyngeal cancers." (PMID 18452596, 2008). "However, in oligodendroglioma specimens, maybe due to the relatively lower progression or richer vascular network, activation of HIF1α was too weak and its poor expression did not associate with VM formation." (PMID 34483751, 2021). "In summary, activation of ATM/ATR but not HIF1α shows a positive correlation with VM formation in oligodendroglioma patients." (PMID 34483751, 2021). "In short, VM formation during the progression of oligodendrogliomas may be regulated by pATM/pATR that participates in multiple essential processes upstream of VM independent of HIF1α." (PMID 34483751, 2021).